SFRP1 (secreted frizzled related protein 1)
Diseases named in the same sentence as SFRP1 in open-access papers (continued):
Sharing a sentence is not in itself a finding about the gene and the disease.
breast carcinoma (continued). "Nevertheless, the RT-qPCR and the IHC data both showed for the first time that SFRP1 expression correlated negatively with Metpos status and tumour grade in CMTs, supporting its potential role as a suppressor of breast cancer progression." (PMID 37402051, 2023). "In general, SFRP1 predicted the therapeutic response of breast cancer indecently of the Wnt signal pathway." (PMID 37963835, 2023). "The scatter diagrams showed that SFRP1 was positively correlated with FMO2 in breast cancer in gene chip data and RNA-sequence data." (PMID 37963835, 2023). "Mechanically, FMO2 was positively and highly correlated with secreted Frizzled-related protein 1 (SFRP1), which was downregulated in breast cancer due to hypermethylation." (PMID 37963835, 2023). "A study based on breast cancer cell lines reported that SFRP1 protein level varied according to breast cancer subtype." (PMID 37999144, 2023). "We saw that, indeed, breast cancer cell lines from luminal subtypes express less SFRP1 than those from basal subtypes, and that normal breast cell lines express a higher SFRP1 level than invasive breast cancer cell lines." (PMID 37190179, 2023). "In order to further assess the potential role of SFRP1 in reducing luminal A breast cancer aggressiveness, we compared the proliferative and migratory abilities of the MCF7 cell line according to SFRP1 modulation of expression." (PMID 37190179, 2023). "This is common in primary breast cancers and occurs early during mammary transformation, with SFRP1 expression being consistently lower in atypical hyperplasia compared to histologically normal breast tissue." (PMID 37402051, 2023). "This is consistent with the overwhelming evidence for SFRP1’s role as a tumour suppressor in human breast cancer formation and progression." (PMID 37402051, 2023). "The pan-cancer analysis indicated SFRP1 mRNA expression is downregulated in various cancers, including breast cancer." (PMID 37963835, 2023). "Then we identified that SFRP1 was positively correlated with FMO2 in breast cancer through the Venn diagram and ranks." (PMID 37963835, 2023). "Luminal A breast cancer patients with high SFRP1 expression had a better RFS (HR = 0.58; logrank p = < 0.01) and OS (HR = 0.73; logrank p = < 0.001) than patients with low SFRP1 expression." (PMID 37190179, 2023). "In order to further understand the impact of SFRP1 on breast cancer progression, we then overexpressed it in the basal-like invasive ductal carcinoma MCF10CA1a cell line." (PMID 37190179, 2023). "In a study of nearly 2000 breast cancers Sfrp1 mRNA was down-regulated in nearly 3/4 of invasive breast cancers with unfavourable prognosis in early breast cancer." (PMID 37402051, 2023). "The Clinical Proteomic Tumor Analysis Consortium (CPTAC) database including 125 breast cancer patients and 18 normal patients showed that SFRP1 protein expression was downregulated (P < 0.0001)." (PMID 37963835, 2023). "We next compared SFRP1 expression in different subtypes of breast cancer according to different clinical indicators." (PMID 37963835, 2023). "In particular, changes in SFRP expression in cancer tissue has been widely observed, with SFRP1, -3, -4, and -5 commonly downregulated in human breast cancer tissues compared to healthy controls." (PMID 37402051, 2023). "This is in line with a recent report that high SFRP1 expression was related to favourable long-term survival in breast cancer patients." (PMID 37391533, 2023). "Luminal B breast cancer patients with high SFRP1 expression had a better prognosis in term of RFS (HR = 0.74; logrank p = < 0.01) and OS (HR = 0.66; logrank p = < 0.05) than patients with low SFRP1 expression." (PMID 37190179, 2023). "The following genes were reported to be higher expressed in breast cancer samples of cases compared to controls in two different studies but were reported to be lower expressed in another study: SFRP1, ACTR1B, FASTK, TMEM219, NDUFA3, ATP5I." (PMID 36627894, 2022).
breast carcinoma (continued). "For the secondary assay, the empty vector-transfected breast cancer cells were used to investigate the potential effects of the SFRP1 mimetic hits on target gene regulation." (PMID 36139547, 2022). "SFRP1 exerts as a tumor suppressor by repressing Wnt/β-catenin pathway in multiple tumors, such as breast cancer, head and neck squamous cell carcinoma and skin squamous cell carcinoma, and ovarian cancer." (PMID 35860691, 2022). "Promoter hypermethylation of SFRP1, 2, 4, and 5 has been reported which correlates with the expression and cancer stage in case of breast cancer and colorectal cancer." (PMID 34552611, 2021). "One study has suggested that SFRP1 plays an additional inhibitory role in breast cancer by blocking the activity of thrombospondin-1 (TSP1), which is involved in the modulation of adhesion and migration of cancer cells." (PMID 32074995, 2020). "In breast cancer, SFRP1 knockdown activates the TGF-β signaling and further increases the expression of ZEB2, zinc finger clusters, that play a critical role in facilitating the EMT process." (PMID 32074995, 2020). "They demonstrated a strong negative correlation between both, suggesting that hypermethylation of SFRP1 promoter is responsible for SFRP1 silencing in breast cancer." (PMID 31947616, 2020). "The aggressiveness of breast cancer is associated with high promoter methylation of TWIST, SFRP1, ESR1, P16, and APC in lymph node positive breast cancer cases." (PMID 32183060, 2020). "Several studies have demonstrated that SFRP1 in breast cancer is downregulated at both the mRNA and protein levels." (PMID 31947616, 2020). "Expression of SFRP1 was found to be significantly higher in TNBC than in other breast cancer subtypes." (PMID 31134153, 2019). "It has been proven that c-MYC transforms human mammary epithelial cells through the repression of the Wnt inhibitors DKK1 and SFRP1 in breast cancer cell lines." (PMID 30866868, 2019). "Copy-number alterations (CNAs) of SFRP1 confer survival disadvantage to breast cancer patients and alter the mRNA expression of SFRP1 in cBioPortal database." (PMID 29371858, 2018). "Studies have reported that miR-27a affects in vivo and in vitro proliferation, migration, and invasion of breast cancer cells through targeting the SFRP1 gene via Wnt/β-catenin signaling pathway." (PMID 29371858, 2018). "In this study, we detected reduced serum levels of DKK1 and SFRP1 in breast cancer survivors following a long-term (12-week) exercise program." (PMID 28178355, 2017). "Conversely, breast cancer cells overexpressing SFRP1 (MCF7-SFRP1) express less EGR2 when compared with vector transfected cells (MCF7-pCDNA) and exogenous rSFRP1 treatment reduces EGR2 expression in MCF7 cells." (PMID 28687085, 2017). "SFRP1 is a member of this protein family and is significantly down-regulated in breast tumors and in breast carcinoma cell lines." (PMID 28687085, 2017). "We demonstrated that long-term exercise decreases the serum levels of DKK1 and SFRP1 and improves physical fitness and biomarker levels related to metabolic conditions in breast cancer survivors." (PMID 28178355, 2017). "The levels of DKK1 and SFRP1 were also significantly decreased by exercise training in breast cancer survivors (all p < 0.01)." (PMID 28178355, 2017). "SFRP1 is a known inhibitor of Wnt pathway and tumor suppressor gene, which is epigenetically silenced in a variety of tumors including breast cancer." (PMID 26618778, 2015). "SFRP1 was identified as being significantly overexpressed in TNBC compared to other breast cancer subtypes." (PMID 25033833, 2014). "Nevertheless, too little is known about signaling pathways modulated by SFRP1 expression in dependency of the molecular breast cancer subtypes." (PMID 25036590, 2014). "In this study, we performed a systematic expression analysis of stably transfected human breast cancer cells to determine those molecules and biochemical pathways affected after forced SFRP1 re-expression." (PMID 25036590, 2014).
breast carcinoma (continued). "In order to better understand SFRP1 function and biological processes involved in SFRP1 mediated target gene modulation in dependency of a distinct breast cancer subtype we performed a gene ontology analysis (GO) in the BT20 and SKBR3 tumor models." (PMID 25036590, 2014). "In breast cancer development SFRP1 promoter hypermethylation has been found to occur frequently (>65%) as well which is furthermore associated with unfavorable prognosis." (PMID 25036590, 2014). "Although BDNF has been postulated as a putative oncogene, the co-regulation with SFRP1 indicates a potential suppressive function in breast cancer." (PMID 25036590, 2014). "This would be in line with previously published data showing reduced xenograft growth after SFRP1 overexpression in breast cancer cells presumably due to blockade of canonical Wnt signaling activity." (PMID 25033833, 2014). "To address this question we initiated a systematic whole genome expression analysis to determine biochemical pathways as well as novel target genes that are affected by SFRP1 in both luminal-like and basal-like breast cancer cells." (PMID 25036590, 2014). "Amongst the differentially expressed genes, we identified downregulation of secreted frizzled-related protein-1 (SFRP-1) in three Her2+ breast cancer cell lines." (PMID 25278993, 2014). "In breast cancer, hypermethylation of the SFRP1 promoter has been correlated to poor prognosis, presumably due to elevated levels of Wnt signaling." (PMID 25033833, 2014). "We found that MDM2 and SFRP1 transcripts were positively correlated with relapse free survival for all breast cancer subtypes and the results were statistically significant." (PMID 25278993, 2014). "In contrast, epigenetic silencing of APC and Wnt ligand inhibitors (sFRP1 and Wif1) have often been reported in primary human mammary tumors and in human breast cancer cell lines." (PMID 24887235, 2014). "Nevertheless, future analyses have to be undertaken to explore the role of SFRP1 in regulating mammary tumor progression, particularly progression of triple negative breast cancer." (PMID 25033833, 2014). "In the present study, seven potential breast cancer marker candidates (SFRP1, SFRP2, SFRP5, WIF1, DKK3, ITIH5, and RASSF1A) were studied with regard to early breast cancer detection in serum." (PMID 23320751, 2013). "sFRP1 and β-catenin were highly expressed in BCSCs from ER+ve breast cancer cell lines (MCF7 and T47D)." (PMID 23861811, 2013). "Of note, Low SFRP1 expression in human breast cancer has been reported by several groups independently." (PMID 21281469, 2011). "In human breast cancer, secreted Frizzled protein (sFRP-1), a member of the Wnt antagonist family, is downregulated in malignant tissues." (PMID 21767405, 2011). "As expression of SFRP1 in breast cancer counteracts Wnt signaling, we proposed that its reduction leads to enhanced Wnt signaling in breast cancer cells." (PMID 21281469, 2011). "The present study indicates that a reduction in SFRP1 expression allows 76 N TERT cells to acquire many of the properties observed in breast cancer cells." (PMID 19422694, 2009). "In summary, the results presented here show that sFRP1-mediated blockade of WNT signaling in MDA-MB-231 breast cancer cells has an impact on the in vitro proliferation and motility of the cancer cells." (PMID 19473496, 2009). "Interference with autocrine WNT signaling via sFRP1 has been shown to block in vitro proliferation of human breast cancer cell lines." (PMID 19473496, 2009). "Like RASSF1A, SFRP1 has also been shown to be silenced through promoter methylation in breast cancer." (PMID 19995452, 2009). "SFRP1 is a member of this protein family that is significantly downregulated in breast tumors and in breast carcinoma cell lines." (PMID 19422694, 2009).
breast carcinoma (continued). "Associated with their early progression to malignancy was an increase in the number of genes methylated, two of which (RASSF1A and SFRP1) were also methylated in other immortalized mammary cell lines as well as in breast cancer cells and tissues." (PMID 19995452, 2009). "One recent study has demonstrated SFRP1 can inhibit the canonical Wnt/β-catenin pathway in breast cancer cells." (PMID 19586554, 2009). "Our results demonstrate the potential of endogenous SFRP1 to inhibit the Wnt/β-catenin pathway in breast cancer cells." (PMID 18283316, 2008). "Consistent with that idea, we have previously found that SFRP1 is methylated in several breast cancer cell lines, and two other groups recently reported frequent SFRP1 methylation in both primary and cultured breast cancer cells." (PMID 18283316, 2008). "To clarify the functional role of SFRP inactivation in breast cancer, we used siRNA to disrupt endogenous SFRP1 expression." (PMID 18283316, 2008). "In breast cancer, SFRP1 and SFRP5 have been identified as targets of aberrant epigenetic inactivation to date, and either promoter methylation was found to be associated with unfavorable patient prognosis." (PMID 18990230, 2008). "We observed SFRP1 methylation in 7 of the 11 (64%) breast cancer cell lines tested (MCF-7, MDA-MB-231, T-47D, SK-BR-3, MDA-MB-361, MDA-MB-453 and ZR-75-1)." (PMID 18283316, 2008). "In human breast cancer, we have previously shown that the SFRP1 and SFRP5 promoter is epigenetically silenced in 61% and 73% of invasive breast carcinomas, respectively, each of which was associated with unfavorable patient prognosis." (PMID 18990230, 2008). "SFRP1 is believed to be a tumor suppressor in human breast cancer." (PMID 38554160, 2024). "Although SFRP1 is downregulated in most breast cancers, this is not the case in the medullary type often associated with triple-negative breast cancers (TNBC), characterised by their lack of hormone receptors ER/PR and HER2." (PMID 37402051, 2023). "We also detected molecular-level perturbations in the expression patterns of several genes linked to breast cancer and cholesterol signalling pathways using RT2-PCR arrays and have identified SFRP1 as a direct binding partner to HPβCD through SPR drug interaction analysis." (PMID 37345165, 2023). "Furthermore, both gene chip data and RNA sequencing data showed that SFRP1 mRNA expression in breast cancer was significantly reduced, and the expression in metastatic breast cancer is lower." (PMID 37963835, 2023). "SFRP1 in breast cancer stroma tended to be lower in patients who were alive at this follow-up time." (PMID 37091166, 2023). "Similarly, gene expression profiling of micro-dissected breast cancer samples from patients with matched IDC, DCIS and associated stroma found that Sfrp1 mRNA was reduced in the neoplastic epithelium during the progression from DCIS to IDC." (PMID 37402051, 2023). "In addition, correlation analysis showed that SFRP1 is the most potentially related (positively) gene, and more importantly, SFRP1 expression was downregulated in breast cancer patients, which was consistent with FMO2 expression." (PMID 37963835, 2023). "SFRP1 interferences with Wnt signaling to block the ligand-receptor interaction or co-regulates with BDNF to have a potential inhibitory effect on breast cancer." (PMID 37963835, 2023). "Furthermore, we have modulated SFRP1 expression in breast cancer cell lines, including the MCF10A series, and investigated their tumoral properties." (PMID 37190179, 2023). "Previous studies have shown that SFRP1 can be used as a prognostic marker in breast cancer and SFRP1 might be used as a marker for chemotherapy and neoadjuvant chemotherapy response in triple-negative breast cancer." (PMID 37963835, 2023). "In addition, the decrease in SFRP1 expression in luminal breast cancer tissue seems induced by an increase in SFRP1 promoter methylation." (PMID 37190179, 2023).
breast carcinoma (continued). "In order to further assess if the increase in SFRP1 expression could potentially decrease luminal A breast cancer progression, we overexpressed SFRP1 in the MCF7 cell line." (PMID 37190179, 2023). "Thus, in order to better understand the impact of SFRP1 on breast cancer progression, we decided to overexpress it in this cell line, investigating the potential of SFRP1 to decrease pre-invasive breast cancer aggressiveness in vitro." (PMID 37190179, 2023). "sFRP1 is also downregulated via multiple miRNAs in breast cancer." (PMID 34552611, 2021). "Hence, this explains the migratory and invasive characteristics exhibited by SFRP1 knockdown in breast cancer cells." (PMID 32074995, 2020). "To explore if re-expression of SFRP1 could reverse the changes, we used MCF7 breast cancer cells which lack SFRP1 expression and compared effects of over-expression (MCF7-SFRP1 vs MCF7-pCDNA)." (PMID 31248446, 2019). "Regulating the target genes YWHAB, LY9 and SFRP1 may be a possible mechanism of has-miR-542-5p in TamR of breast cancer." (PMID 29371858, 2018). "For instance, a prognostic predictor of breast cancer, SFRP1, was found the second modulator." (PMID 28984209, 2017). "Likewise, SIRT1 localizes to the promoter of sFRP1 and directly contributes to the aberrant epigenetic silencing of breast cancer cells." (PMID 27776347, 2016). "Additionally, we evaluated the molecular mechanisms by which SFRP1 alters the carcinogenic properties of breast cancer cells." (PMID 25033833, 2014). "By analyzing the molecular role of SFRP1 in triple negative breast cancer cells via siRNA mediated knockdown we found changes in carcinogenic properties of breast cancer cells, e.g. increased migration and invasion potential as well as reduced apoptotic events." (PMID 25033833, 2014). "Next, we sought to explore the impact of SFRP1 on tumorigenic properties of breast cancer cells." (PMID 25033833, 2014). "Thus, the immunohistochemical analysis of human breast cancer specimens again confirmed that BDNF is a potential “SFRP1 target gene” as originally predicted by our microarray analysis." (PMID 25036590, 2014). "To that end we analyzed SFRP1 expression in 85 breast cancer tissue samples by real-time PCR." (PMID 25036590, 2014). "Furthermore, to our best knowledge the current findings propose for the first time that BDNF is a target gene of SFRP1 with putative suppressive characteristics in breast cancer, thus highlighting its clinical relevance in a completely different and novel way." (PMID 25036590, 2014). "Moreover it has been clearly shown that SFRP1 re-expression led to a decreased in vitro tumor cell proliferation of human breast cancer cells." (PMID 25036590, 2014). "By using a published dataset analyzing differential gene expression profiles as well as response to neoadjuvant chemotherapeutic treatment of breast cancer patients we could show a correlation of SFRP1 expression and the triple negative breast cancer subtype." (PMID 25033833, 2014). "However, combined analysis of weak BDNF and weak SFRP1 expression predicted also an unfavorable patients' outcome underscoring the significance of the breast cancer model-based SFRP1/BDNF expression axis." (PMID 25036590, 2014). "Of interest distinct Wnt signaling pathways may be triggered by SFRP1 in dependency of different breast cancer subtypes." (PMID 25036590, 2014). "In summary, we could show that tumor suppressor and Wnt signaling antagonist SFRP1 is correlated with the most aggressive subtype of breast cancer, i.e. triple negative breast cancer; but also with positive response to neoadjuvant chemotherapy." (PMID 25033833, 2014). "Hence, we analyzed both migration as well as invasion potential of breast cancer cell line MDA-MB-468 after SFRP1 knockdown." (PMID 25033833, 2014). "This could indeed indicate that there is a physiological relevance for SFRP1-BDNF expression axis found in human breast cancers." (PMID 25036590, 2014).